TXNRD1 (thioredoxin reductase 1)
Diseases named in the same sentence as TXNRD1 in open-access papers (continued):
Sharing a sentence is not in itself a finding about the gene and the disease.
small cell lung carcinoma (1 paper, 2022). Small cell lung cancer (SCLC) is a highly aggressive malignant neoplasm, accounting for 10-15% of lung cancer cases, characterized byrapid growth, and early metastasis. "Accordingly, a study showed that auranofin, an irreversible inhibitor of TXNRD1, in combination with GSH depletion can induce ferroptosis in small cell lung cancer (SCLC)." (PMID 35912247, 2022).
Stroke (1 paper, 2008). Sudden impairment of blood flow to a part of the brain due to occlusion or rupture of an artery to the brain. "Our data imply that it is Txnrd1 and not Txnrd2 that plays a critical role in brain development, however this does not rule out any contribution of Txnrd2, for instance under pathological conditions such as stroke and trauma." (PMID 18350150, 2008).
tauopathy (1 paper, 2022). Neurodegenerative disorders involving deposition of abnormal tau protein isoforms (tau proteins) in neurons and glial cells in the brain. "Interestingly, Mical excess decreased the interaction between Tau and Thioredoxin reductase-1 (Trxr), whereas downregulation of Trxr antioxidant activities was shown to enhance neurodegeneration in a Drosophila Tauopathy model." (PMID 35379354, 2022).
Tinnitus (1 paper, 2022). Tinnitus is an auditory perception that can be described as the experience of sound, in the ear or in the head, in the absence of external acoustic stimulation. "For the first time, we identified WNT8A to be genome‐wide significant for tinnitus and TXNRD1 as having borderline genome‐wide significance for hearing loss following cisplatin treatment through a gene‐based association analysis." (PMID 35322580, 2022).
cancer (194 papers, 2007 to 2026). A tumor composed of atypical neoplastic, often pleomorphic cells that invade other tissues. "TXNRD1 functions as maintaining redox homeostasis and decreasing the mutation of normal cells that lead to cancer." (PMID 36319631, 2022). "Targeting TXNRD1 results in accumulation of reactive oxygen species, causing cancer cells to experience high levels of oxidative stress." (PMID 32953265, 2020). "Our results also suggested that endogenous levels of TXNRD1 expression in cancer cells are inversely associated with auranofin's activity, and causally associated with the resistance to auranofin in NSCLC cells." (PMID 26657290, 2016). "Three selenoproteins have been implicated in both prevention and promotion of cancer: the 15kDa selenoprotein (Sep15), thioredoxin reductase 1 (Txnrd1, TR1), and glutathione peroxidase 2 (GPx2)." (PMID 25886253, 2015). "Therefore, inhibition of SLC7A11 together with the inhibition of TXNRD1 predisposes cancer cells to “disulfide stress”, and further induces cell death." (PMID 35453395, 2022). "Therefore, further investigations are needed into the role of TXNRD1-targeted inhibitors on cancer and the underlying mechanisms." (PMID 33706760, 2021). "Survival analysis revealed that the expression levels of these genes were closely related to patient survival, but the directions of the associations differed between different types of cancer, except for the TXNRD1 and TXNRD3 genes, which showed significant adverse prognoses in all cancer types." (PMID 33706760, 2021). "Enhanced ROS sensitivity of cancer cells could also be attributed to depletion of the reduced thioredoxin (Trx-SH) pool caused by the inhibition of thioredoxin reductase 1 (TrxR1) by curcumin." (PMID 32765806, 2020). "Moreover, we also found the patients with high risk scores had increased TXNRD1 expression, consistent with the findings in other cancer types." (PMID 29910195, 2018). "TXNRD1 is highly expressed in many cancers, and has been linked with tumor development." (PMID 30619751, 2018). "TXNRD1 inhibition can lead to an impairment of required antioxidant capacity particularly in cancer cells, while normal cells can survive a loss of TXNRD1 activity, it is thus not far-fetched to propose that TXNRD1 inhibition may be a potential mechanism of action for anticancer drugs." (PMID 36319631, 2022). "Besides, TXNRD1 is actually associated with normal cell survival, division, migration, and proliferation; however, it has been reported to be up-regulated in numerous cancer cells." (PMID 35453395, 2022). "In addition, many TXNRD1-inhibiting drugs can simultaneously activate Nrf2, which helps to protect normal cells from oxidative damage so as to inhibit their induction and transformation associated with cancer." (PMID 33706760, 2021). "Piperlongumine inhibits cytosolic thioredoxin reductase (TXNRD1) and has been found to destroy cancer cells." (PMID 40916076, 2025). "The data above support a model in which PK11007 inhibits TXNRD1 activity, leading to ROS-driven oxidative stress, impaired autophagy, and cancer cell death." (PMID 41154531, 2025). "This highlights a gap in our understanding of auranofin’s anti-cancer activity and our need to better understand how TXNRD1 inhibition affects not only tumor-intrinsic redox states but also the immune microenvironment." (PMID 41300507, 2025). "Recent studies have highlighted the potential of targeting oxidative stress regulation in cancer therapy, including inhibition of antioxidant selenoproteins such as TXNRD1 and upstream regulators like NRF2." (PMID 40818321, 2025). "In lung cancer, elevated TXNRD1 levels contribute to resistance against therapies such as cisplatin by maintaining low intracellular ROS levels, thereby shielding cancer cells from oxidative damage." (PMID 41333220, 2025).
cancer (continued). "Selenoprotein thioredoxin reductase 1 (TXNRD1) is frequently upregulated in various cancer cells to sustain cellular redox homeostasis, and its inhibition has emerged as a promising anti-cancer strategy." (PMID 41154531, 2025). "Low concentrations of piperlongumine do not induce ferroptosis, but piperlongumine enhances erastin-induced cell death in cancer cells by inhibiting the activity of TXNRD1." (PMID 40552277, 2025). "One proposed mechanism of cancer cell death induced by TXNRD1 inhibition is SecTRAPs (selenium compromised thioredoxin reductase-derived apoptotic proteins)." (PMID 41154531, 2025). "Clusters 3 and 5 showed elevated expression of genes associated with cancer development and progression, such as CEBPB, PLIN2, PRDX1, PSMD6, and TXNRD1." (PMID 39805002, 2025). "TXNRD1 is frequently upregulated in a variety of human cancers and supports tumor cell survival under oxidative stress." (PMID 41154531, 2025). "TXNRD1 inhibitors, such as auranofin, impairs anti-cancer immune responses in immunocompetent mice by promoting regulatory T cell expansion through elevating ROS levels." (PMID 41300507, 2025). "Several reports have demonstrated that increases in TXN and TXNRD1 under glucose deprivation conditions support cancer cell survival and migration 62, 63, whereas enhanced stability of TXNIP mRNA inhibits tumor metastasis and glycolysis." (PMID 39744566, 2025). "Suppressing the production of ROS in cancer cells, thioredoxin reductase 1 (TR1) is stimulated subsequent to activation, thereby inducing resistance to 5-fluorouracil." (PMID 39286246, 2024). "Targeting TXNRD1 to promote cancer cell death due to oxidative stress disorder has the potential to be a new target for cancer therapy." (PMID 38167017, 2024). "M-E4BP4 showed increased expression of anti-inflammatory genes such as Retnla, IL10, and C1qa, and Ccl5, which is involved in immune escape of cancer, and decreased expression of pro-inflammatory genes such as Txnrd1, Odc1, Mmp1232,36–40." (PMID 38714733, 2024). "Recent studies have reported ROS induction can be increased in cancer cells by targeting thioredoxin reductase 1 (TrxR1) and by depleting the cellular glutathione (GSH) level." (PMID 37397502, 2023). "Due to its central role in ROS scavenging and signaling pathways, TXNRD1 is a prototypic target for ROS-inducing cancer therapy." (PMID 36958250, 2023). "Apart from the stressed oligomerized forms, TXNRD1 is generally a homodimeric selenoenzyme with a highly reactive selenocysteine at position 498, which has been considered a potential drug target in cancer therapy." (PMID 37836684, 2023). "Our data clearly revealed that chelerythrine and sanguinarine irreversibly inhibit the activity of TXNRD1 while specifically targeting Sec498 of the enzyme, presenting significant anti-cancer activities through necroptotic cell death." (PMID 37836684, 2023). "Cancer cells up-regulate the expression of TXNRD1 to control excessive reactive oxygen species (ROS) generated from anabolic and catabolic processes." (PMID 37836684, 2023). "Cytosolic selenoenzyme thioredoxin reductase 1 (TXNRD1) plays important roles in various human diseases and is a vital target in cancer therapy." (PMID 37836684, 2023). "Regulating cellular phenotypes, cellular growth, and responses to stimuli, TXNRD1 is related to various cancer diseases and is also a popular target for cancer." (PMID 36578523, 2022). "The antineoplastic activity of the thioredoxin reductase 1 (TrxR) inhibitor, auranofin (AF), has already been investigated in various cancer mouse models as a single drug, or in combination with other molecules." (PMID 36559255, 2022). "The pan-cancer analysis results suggest that the eight hub genes (TXNRD1, TUBG1, SF3B4, PPM1G, PIGU, NDRG1, GRPEL2, and EZH2) were differentially expressed in gastrointestinal tumors." (PMID 36686830, 2022).
cancer (continued). "Aside from direct inhibition of TXNRD1, other studies in cancer have focused on the regulation of TXNRD1 through its transcription factor nuclear factor-erythroid factor 2 (Nrf2)." (PMID 36358931, 2022). "Nevertheless, as the involvement of TXNRD1 in ferroptosis is a novel finding, there are still details to explore and uncover, particularly in relation to its role in cancer cell growth and development." (PMID 36358931, 2022). "In order to target the Sec residue of TXNRD1 to induce cancer cell death, various electrophilic small molecules have been screened, designed, and developed so far." (PMID 35453395, 2022). "What is more, published studies show the survival of diverse cancer cell types that lack TXNRD1 genetically, but pharmacological inhibition of TXNRD1 induced robust cancer cell apoptosis." (PMID 35453395, 2022). "The cytoplasmic selenoprotein thioredoxin reductase 1 (TXNRD1) has several different effects related to cancer including the protection of normal cells to evolve into cancer cells or the protection against the promotion of cancer progression." (PMID 35308531, 2022). "Meanwhile, piperlongumine sensitizes cancer cells to erastin, which underscores the predominant roles of TXNRD1 in cancer cell ferroptosis." (PMID 35453395, 2022). "Taken together, this study elucidates the molecular mechanism of the antitumor capacity of piperlongumine by targeting TXNRD1 and reveals the potential possibility of inhibiting TXNRD1 to strengthen cancer cells’ ferroptosis." (PMID 35453395, 2022). "Despite limited evidence, these findings intimate that TXNRD2 and TXNRD3 also inhibit oxidative stress via the thioredoxin system in cancers as TXNRD1, thereby promoting cancer cell resistance to cell death." (PMID 36358931, 2022). "Still, several lines of evidence suggest that TXNRD1 is involved in regulating ferroptosis in cancer." (PMID 36358931, 2022). "TXNRD1 is a critical selenoprotein in cancer cells, and found to be overexpressed in several cancer types when compared to TXNRD2 and TXNRD3." (PMID 36358931, 2022). ", is known to inhibit the cytosolic thioredoxin reductase (TXNRD1 or TrxR1) and selectively kill cancer cells." (PMID 35453395, 2022). "Since cancer cells possess high levels of endogenous reactive oxygen species (ROS) and are more sensitive to redox imbalance than normal cells, targeting TXNRD1 to disturb cell redox balance has been exploited as a promising strategy for cancer therapy." (PMID 35453395, 2022). "Since the GSH system and TXN system are the prominent cellular redox regulation systems, an attempt was made to inhibit TXNRD1 activity by piperlongumine to enhance erastin-induced cell death in cancer cells." (PMID 35453395, 2022). "Selenoproteins that are directly or indirectly linked to redox homeostasis maintenance, such as GPXs, TXNRD1, SELENOF, and SELENOP appear to affect multiple signalling pathways involved in cancer initiation and progression." (PMID 35204134, 2022). "NACRT therapeutic efficacy and clinical outcomes in ESCC patients can be predicted by examining TXNRD1 and HO-1 expression status in carcinoma cells in pre-therapeutic endoscopic biopsy and surgically resected specimens." (PMID 34999996, 2022). "Some studies have shown that normal cells can survive after TXNRD1 activity is inhibited, suggesting that a TXNRD1 inhibitor can kill cancer cells directly and selectively." (PMID 33706760, 2021). "The thioredoxins TXN and TXNRD1 were upregulated in the total TCGA cohort and in the EGFRwt group, but less in the EGFRmut group, suggesting differential regulation in cancer cells harboring EGFRwt compared to EGFRmut group." (PMID 33668151, 2021). "This study revealed that SIMR1281 modulates the functions of thioredoxin reductase 1, glutathione reductase, and inositol-3-phosphate synthase, key enzymes that are overexpressed in cancer cells." (PMID 34200264, 2021).
cancer (continued). "A TXNRD1 inhibitor can increase the ROS level of cancer cells and induce cancer cell death by inhibiting TXNRD1 activity." (PMID 33706760, 2021). "The effects on cancer and the potential in new anticancer treatments have been the discussed most widely for the TXNRD1 gene from among the TXNRD family members." (PMID 33706760, 2021). "The corresponding reaction is that cancer cells will accelerate the levels of antioxidant proteins (such as TXNRD1), which can detoxify ROS to maintain redox balance and anti-apoptosis." (PMID 33292234, 2020). "To investigate the possible involvement of TXNRD1 (gene coding for TrxR) expression in patient survival, we retrospectively analyzed microarray datasets of different types of cancer." (PMID 30791480, 2019). "In this study, Kaplan-Meier survival plots generated from cohort data demonstrated that higher expression of TXNRD1 gene is significantly correlated with poor survival outcome, identifying this gene as an unfavorable prognostic factor for cancer patients." (PMID 30791480, 2019). "In German patients, GPX1, GPX4, and TXNRD1 were also found to be up-regulated in cancer, compared to the matched tissues for mRNA and/or their corresponding protein levels." (PMID 30469315, 2018). "The presence of increased ROS levels is a known feature of tumor microenvironment and induction of the thioredoxin/thioredoxin reductase (TXN/TXNRD1) system is known to be beneficial for the survival of cancer cells." (PMID 29755668, 2018). "TXNRD1 has been demonstrated to be overexpressed in many cancers, and ROS level also increased in many tumors, including HCC." (PMID 28536696, 2017). "Several cancers display increased expression of TXN and thioredoxin reductase 1 (TXNRD1) to compensate for GSH deficiency in GCLM−/− cells." (PMID 28744456, 2017). "TXNRD1 promotes tumor growth, DNA replication, and tumorigenicity, and knockdown of TXNRD1 also increases sensitivity of cancer cells to some chemotherapy drugs; these finding suggest it is a potential target for anticancer agents." (PMID 28536696, 2017). "TXNRD1 is highly expressed in different human cancers and is considered to be an important target in chemotherapy." (PMID 29050246, 2017). "TXNRD1 knockdown significantly slowed tumor progression and metastasis in lung carcinomas, but it promoted cancer incidence in liver." (PMID 28744456, 2017). "In this report, we found that addition of thioredoxin reductase 1 (TXNRD1) inhibitor auranofin to the TUSC2/erlotinib combination synergistically enhanced cancer cell death by induction of apoptosis through an increase in ROS." (PMID 27845352, 2016). "TXNRD1 knockdown markedly suppresses tumor progression and metastasis and decreases transcription levels of cancer-related proteins." (PMID 26325518, 2015). "We examined the contributions of the 15kDa selenoprotein (Sep15) and thioredoxin reductase 1 (TR1) to cancer development." (PMID 25886253, 2015). "TXNRD1 is one of key redox regulators in mammalian cells, and therefore helps protect both normal and cancer cells from oxidative stress." (PMID 26569310, 2015). "TXNRD1 regulates the redox state of protein thiols in mammalian cells, and functions in both promoting and preventing cancer in different kinds of carcinomas." (PMID 24926661, 2014). "TXNRD1 is an interesting drug target as its gene was found in our analysis to be up-regulated in cancers compared with normal tissues (group 6)." (PMID 24342878, 2013). "Thioredoxin reductase 1 is a major antioxidant and redox regulator in mammalian cells and has an essential role in mammalian development and cancer." (PMID 23251571, 2012).